CD244 (CD244 molecule)
Description:
Heterophilic receptor of the signaling lymphocytic activation molecule (SLAM) family; its ligand is CD48. SLAM receptors triggered by homo- or heterotypic cell-cell interactions are modulating the activation and differentiation of a wide variety of immune cells and thus are involved in the regulation and interconnection of both innate and adaptive immune response. Activities are controlled by presence or absence of small cytoplasmic adapter proteins, SH2D1A/SAP and/or SH2D1B/EAT-2. Acts as activating natural killer (NK) cell receptor. Activating function implicates association with SH2D1A and FYN. Downstreaming signaling involves predominantly VAV1, and, to a lesser degree, INPP5D/SHIP1 and CBL. Signal attenuation in the absence of SH2D1A is proposed to be dependent on INPP5D and to a lesser extent PTPN6/SHP-1 and PTPN11/SHP-2. Stimulates NK cell cytotoxicity, production of IFN-gamma and granule exocytosis. Optimal expansion and activation of NK cells seems to be dependent on the engagement of CD244 with CD48 expressed on neighboring NK cells (By similarity). Acts as costimulator in NK activation by enhancing signals by other NK receptors such as NCR3 and NCR1. At early stages of NK cell differentiation may function as an inhibitory receptor possibly ensuring the self-tolerance of developing NK cells. Involved in the regulation of CD8(+) T-cell proliferation; expression on activated T-cells and binding to CD48 provides costimulatory-like function for neighboring T-cells (By similarity). Inhibits inflammatory responses in dendritic cells (DCs) (By similarity).
Synonyms: NAIL; NKR2B4; SLAMF4; 2B4; Nmrk
Tractability: Antibody: UniProt places it where antibodies can reach, with high confidence; its Gene Ontology location is reachable by antibodies, with high confidence; UniProt predicts a signal peptide or a membrane-spanning region. PROTAC: its protein half-life has been measured.
Gene: Protein-coding gene on chromosome 1 (160,830,160 to 160,862,904, reverse strand). Ensembl gene ENSG00000122223.
Subcellular location: Membrane; Cell membrane; Membrane raft
Pathways (Reactome):
Hemostasis: Cell surface interactions at the vascular wall
Gene Ontology:
Molecular function: MHC class I protein binding; protein binding; signaling receptor activity
Biological process: natural killer cell activation; natural killer cell activation involved in immune response; positive regulation of granzyme B production; positive regulation of inositol phosphate biosynthetic process; positive regulation of interleukin-8 production; positive regulation of type II interferon production; immune response; signal transduction
Cellular component: external side of plasma membrane; membrane raft; plasma membrane; membrane
Genetic constraint (gnomAD): Loss-of-function variants: 10 observed, 33.88 expected, observed/expected ratio (o/e) 0.3, 90% interval 0.18 to 0.5. The upper end of that interval is the gene's LOEUF score, 0.5, which puts it in group 2 of 6, group 1 being the genes least tolerant of losing a copy. Missense variants: 332 observed, 368.52 expected, observed/expected ratio (o/e) 0.9, 90% interval 0.82 to 0.99. Synonymous variants: 149 observed, 140.72 expected, observed/expected ratio (o/e) 1.06, 90% interval 0.93 to 1.21.
Homologues: Orthologues: chimpanzee CD244 (95% identical), macaque CD244 (82% identical), pig CD244 (60% identical), dog CD244 (55% identical), mouse Cd244a (53% identical), guinea pig Cd244 (49% identical), rat Cd244 (43% identical), rat Cd244l1 (33% identical), zebrafish si:cabz01074946.1 (11% identical). Paralogues in human: CD84 (19% identical), SLAMF7 (18% identical), LY9 (17% identical), SLAMF1 (16% identical), SLAMF8 (16% identical), CD2 (15% identical), SLAMF9 (15% identical), SLAMF6 (15% identical), CD48 (13% identical).
Diseases named in the same sentence as CD244 in open-access papers:
CD244 is named in the same sentence as 120 diseases in open-access papers, as found by Europe PMC text mining. Sharing a sentence is not in itself a finding about the gene and the disease. The quoted sentences say what the papers report.
melanoma (15 papers, 2009 to 2024). A malignant, usually aggressive tumor composed of atypical, neoplastic melanocytes. "Consistent with the murine data, transcriptome analysis of human melanoma tissue single-cell RNA-sequencing dataset revealed close association between CD244 and the inhibition of macrophage maturation and function." (PMID 38424542, 2024). "High expression levels of CD244 were positively associated with immunotherapy response in non-small cell lung cancer, melanoma and hepatocellular carcinoma." (PMID 38633624, 2024). "CD244 levels owned the diagnostic performance in discerning immunotherapy responders in melanoma, non-small cell lung cancer and hepatocellular carcinoma." (PMID 38633624, 2024). "Consistent with the murine data, transcriptome analysis of human melanoma tissue single-cell RNA-sequencing dataset (SCP398 from single-cell portal) revealed close association between CD244 and the suppression of phagocytosis, antigen presentation, and autophagy." (PMID 38424542, 2024). "The presence of CD244-negative monocytes/macrophages and their impact on T cell activity in human melanoma tissues prompted us to evaluate the clinical implications of CD244 on monocyte-lineage cells in the pathogenesis of human melanoma." (PMID 38424542, 2024). "In conclusion, our study highlights the novel role of CD244 on monocytes/macrophages, which restrains the maturation of anti-tumorigenic macrophages and dampens the antigen-specific activation of T cells in melanoma." (PMID 38424542, 2024). "To assess the therapeutic potential of CD244-deficient macrophages in the preclinical setting, we performed adoptive transfer of CD244−/− BMDM in the presence of an anti-PD-L1 antibody to B16 melanoma-bearing WT mice." (PMID 38424542, 2024). "Our study highlights the novel role of CD244 on monocytes/macrophages in restraining anti-tumorigenic macrophage generation and tumor antigen-specific T cell response in melanoma." (PMID 38424542, 2024). "Collectively, CD244 suppressed anti-tumor activity, and its expression was significantly increased in monocytes and macrophages within melanoma." (PMID 38424542, 2024). "Lastly, we examined if our results on CD244 on monocyte-lineage cells can be expanded to other tumor models beyond melanoma." (PMID 38424542, 2024). "For instance, CD244 can mediate immune escape in mice with melanoma by regulating CD4+ and CD8+ T-cell expression." (PMID 36213111, 2022). "Correspondingly, in vivo administration of anti-CD244 mAb significantly decreased the number of B16F10 syngeneic melanoma lung nodules in wildtype (WT) mice following intravenous injection." (PMID 30546369, 2018). "In both of these studies, CD244−/− mice demonstrated increased ability to reject CD48(+) B16 melanoma cells compared with WT." (PMID 30546369, 2018). "Furthermore, conducting cell type deconvolution analysis on bulk RNA-seq datasets from melanoma patients in the TCGA database unveiled that the presence of CD244-negative monocytes/macrophages was associated with a significant increase in patient survival, both in primary and metastatic tumors." (PMID 38424542, 2024). "CD244 also showed an overexpression on the exhausted CD8+ T cells in some human cancers, like melanoma and multiple myeloma." (PMID 37634081, 2023). "These activities inhibit the differentiation of exhaustive CD8+ T cells by decreasing expression of both 2B4 (CD244) and PD-1 while increasing IL-2 and CD127 (IL-7Rα receptor) expression on CD8+ T cells in an OT-I melanoma mouse model." (PMID 31540435, 2019). "While blockade of PD-1 or PD-L1 in combination with IL PV-10 therapy led to anti-tumor immunity in murine melanoma, many CD8+ T cells infiltrating tumors express other co-inhibitory molecules including Tim3, Lag3, CD160, CD244 and BTLA." (PMID 29694419, 2018). "Our observations were further supported by increased autophagy signatures in CD244-negative monocyte-lineage cells from human melanoma patients." (PMID 38424542, 2024).
melanoma (continued). "However, female CD244−/− mice showed poor rejection of both CD48(+) and CD48(–) B16 melanoma cells, suggesting a gender-based difference in these genetically-modified mice." (PMID 30546369, 2018). "In melanoma, CD244 is increased in tumor-infiltrating lymphocytes compared with peripheral blood, and CD8+ T cells from tumor and peripheral blood show increased CD244 expression compared with CD8+ T cells from healthy controls." (PMID 30546369, 2018). "Previous results have shown that CMV pp65-specific CD8+ T cells also showed high expression of CD244 whereas influenza virus-specific and melanoma antigen-specific CD8+ T cells showed low or negative expression of CD244, respectively." (PMID 19997502, 2009). "Finally, the clinical feasibility of CD244-negative monocytes as a therapeutic modality in melanoma was confirmed by adoptive transfer experiments." (PMID 38424542, 2024). "Furthermore, transcriptome analysis of human melanoma patients revealed a potential prognostic significance of CD244-negative monocytes/macrophages in both primary and metastatic tumors." (PMID 38424542, 2024). "To determine the clinical significance of CD244 as an immune checkpoint receptor on monocytes/macrophages within the TME, we re-analyzed a previously reported single-cell RNA-seq dataset (SCP398 from Single Cell Portal) of CD45+ immune cells isolated from human melanoma tissues." (PMID 38424542, 2024). "In a phase 1 trial of patients with melanoma patients and who received melanoma antigen recognized by T-cell 1 (MART1) peptide vaccinations with or without IMP321, those treated with IMP321 presented decreased expression of PD-1, LAG-3, TIM-3, CD244, and CD160." (PMID 37509517, 2023).
Sepsis (12 papers, 2017 to 2024). Sepsis is defined as life-threatening organ dysfunction caused by a dysregulated host response to infection. "PMN-MDSCs isolated from the BM on late sepsis had higher mRNA levels of CD244 and inducible nitric oxide synthase (iNOS)." (PMID 38385073, 2024). "The increased expression of CD244 and its ligands by various immune cells can stimulate immune cell function, but can also contribute to sepsis by disturbing systemic immune function." (PMID 33841431, 2021). "Small molecule or siRNA that could inhibit the expression or block the functional activity of CD244, either alone or in combination, may therefore be an effective therapeutic strategy for sepsis." (PMID 33841431, 2021). "Thus, like most co-inhibitory molecules, CD244 plays a crucial role in establishment of the immunosuppressive environment in patients with sepsis." (PMID 33841431, 2021). "However, detailed loss-of-function studies are necessary to assess the role of CD244 expressed on MDSCLT in sepsis because CD244 also plays crucial roles in NK cell functions and NK cells contribute to antibacterial immunity via crosstalk with other immune cells." (PMID 30279688, 2018). "We did find the increased expression of CD244 in PMN-MDSCs of late septic mice, indicating that it may be more suitable for sepsis-related studies." (PMID 38385073, 2024). "Previous studies indicated that CD244 can affect the onset and progression of autoimmune diseases (SLE and RA), chronic viral infections, tuberculosis, sepsis, and other diseases by altering the function of NK cells, T cells, monocytes, DCs, MDSCs, and other immune cells." (PMID 33841431, 2021).
systemic lupus erythematosus (11 papers, 2017 to 2025). An autoimmune multi-organ disease typically associated with vasculopathy and autoantibody production. "CD244 is known as an important regulator of various autoimmune defects, where low expression of CD244 on monocytes can cause systemic lupus erythematosus and the overexpression of CD244 could accelerate the cancer pathogenesis." (PMID 32153632, 2020). "According to different research, several autoimmune conditions such as rheumatoid arthritis (RA) and systemic lupus erythematosus (SLE) have different amounts of CD244 expression." (PMID 39423200, 2024). "Notably, decreased CD244 expression has been observed in monocytes isolated from patients with systemic lupus erythematosus (SLE), an autoimmune disease in which monocyte differentiation and polarization into pro-inflammatory macrophages have been implicated in disease pathogenesis." (PMID 38424542, 2024).
leukemia (10 papers, 2014 to 2023). A malignant (clonal) hematologic disorder, involving hematopoietic stem cells and characterized by the presence of primitive or atypical myeloid or lymphoid cells in the bone marrow and the blood. "Beside the commonly targeted AML-associated antigens, CD244 and TIM3 have been reported to be overexpressed on LSC and to have a direct leukemia-promoting effect by maintaining the proliferative capability of LSC." (PMID 29946192, 2019). "Some of the NK cell receptors are already found to be valuable for leukemia treatment and tumor surveillance, which were PD-1, 2B4 (CD244), CS1(CD319), LLT1 (CLEC2D) that regulate NK cell cytotoxicity, and NKp44, NKp30, and NKp46 known as natural cytotoxicity receptors (NCRs)." (PMID 37078002, 2022). "Apart from Cxcr4, the screen also identified Cd47 and Cd244 (also referred to as 2B4) as positive regulators of MLL-AF9 leukemia cells in vivo; both are known to play a role in immune regulation in normal hematopoiesis and to promote AML cell growth and survival." (PMID 32460032, 2020). "CD244 may therefore represent a unique therapeutic target if future studies confirm its role as a direct anti-leukemia target and support the hypothesis that it mediates immunosuppressive function in the tumor microenvironment." (PMID 30546369, 2018). "A recent study shows that knock-down of CD244 in human leukemia cell lines produces markedly impaired proliferation in vitro and in vivo, while the repopulation ability of hematopoietic stem cells remains unimpaired following CD244 knockdown." (PMID 30546369, 2018). "Expression levels of CD244 and CD160, which are expressed in severely exhausted T cells, did not significantly differ between non-leukemic mice and mice with advanced leukemia." (PMID 26658107, 2015).
tuberculosis (10 papers, 2013 to 2025). A chronic, recurrent infection caused by the bacterium Mycobacterium tuberculosis. "It is known that CD244 signalling correlates with certain virus persistence in humans, namely hepatitis B, hepatitis C, and tuberculosis (TB)." (PMID 41272580, 2025). "In patients with active tuberculosis, the cross-linking activation of the CD244/2B4 signaling pathway inhibits the production of IFN-γ, possibly due to its inhibitory effect on Mycobacterium tuberculosis antigen-specific CD4+ T cell function." (PMID 38980684, 2025). "A previous study also found out that in tuberculosis, as a chronic infection, the expression of CD244 and then LncRNA-GSTT1-AS1, known as LncRNA-CD244, increased in CD8+ T cells, which led to decreased IFN- and TNF- production and impaired immune response to infection." (PMID 37634081, 2023). "In summary, our study demonstrated that CD244/2B4 expression on M. tuberculosis antigen-responsive CD4+ T cells was significantly higher in active TB patients than in latent TB infection individuals." (PMID 23638187, 2013). "Taken together, these results indicate that active TB patients have significantly elevated expression of CD244/2B4 on M. tuberculosis antigen-responsive CD4+ T cells." (PMID 23638187, 2013). "Active TB patients had significantly elevated CD244/2B4 expression on M. tuberculosis antigen-specific CD4+ T cells compared with latent infection individuals." (PMID 23638187, 2013). "According to previous reports, infection of viruses, such as tuberculosis, induces CD8+ T cells to upregulate CD244 and lncRNAs of the CD244 signaling pathway epigenetically regulate CD8+ T cell immune responses." (PMID 36845111, 2023). "However, there is evidence that patients with active tuberculosis (TB) achieve immune suppression due to increased expression of CD244 by many immune cells, including CD4+ T cells and myeloid-derived suppressor cells (MDSCs)." (PMID 33841431, 2021). "When only M. tuberculosis culture-positive TB cases were selected for analysis, retreatment TB patients were found to have higher frequencies of CD244/2B4-expressing antigen-responsive CD4+ T cells than latent infection individuals (p = 0.0098) and new TB patients (p = 0.0339) as well." (PMID 23638187, 2013). "Because the microarray data showed increased expression of CD244 in MDSCLT compared with MDSCL (fold change = 2.7 ± 1.1) and the CD244hi MDSC population was significantly increased in tuberculosis patients and in tumor-bearing mice, we analyzed the expression of CD244 on MDSCLT." (PMID 30279688, 2018).
viral infection (10 papers, 2012 to 2024). "Chronic viral infection is associated with T cell exhaustion manifested by sustained expression of inhibitory receptors such as PD-1, 2B4 (CD244), CTLA4, LAG3, TIM3, CD16022." (PMID 32020034, 2020). "These potential mechanisms include NF-kB-mediated immune response (i.e. PIDD1), immune synaptic interaction involved in T cell activation (i.e. CD151) and T cell exhaustion in viral infection (i.e. CD244)." (PMID 34027315, 2021). "Levels of CD244 (a pluripotent immunoreceptor) were reduced in MIS-C and bacterial infection in comparison with viral infection and KD." (PMID 39300098, 2024). "Consistently, increased levels of both CD244 and CD160 in patients infected SARS-CoV-2 and other viruses indicated that T cell aging occurred as well as exhaustion in viral infection." (PMID 35386693, 2022). "Its ligand is CD48, and the CD244/CD48 interaction regulates target cell lysis by NK cells and CD8+ cytotoxic T cells, in addition to participating in the fight against viral infection and regulation of effector/memory T cell generation and survival." (PMID 31138840, 2019). "Furthermore, their CTLs expressed PD-1 and LAG-3, but not CD244 and CD160, at significantly higher levels than those of non-leukemic mice, a phenotype resembling exhaustion during chronic virus infection." (PMID 26658107, 2015).
glioma (9 papers, 2017 to 2024). A benign or malignant brain and spinal cord tumor that arises from glial cells (astrocytes, oligodendrocytes, ependymal cells). "Glioma-associated DEGs CD244, IL21, RET, TGFA were up-regulated and AQP9, IGFBP2, EGFR, SOX9 were down-regulated specifically in the rat." (PMID 29352201, 2018). "We observed that PTPN18 expression was positively correlated with six immunosuppressive genes (PD-L1, PD-1, CTLA4, LAG3, HAVCR2, and CD244) in most cancers, including glioma." (PMID 36846716, 2023). "Other immune checkpoint molecules, including lymphocyte activation gene-3 (LAG-3; also known as CD223), 2B4 (also known as CD244), B and T lymphocyte attenuator (BTLA; also known as CD272), have not been fully explored for their biological activities and functions in glioma." (PMID 27756892, 2017). "Further, Tim-3 and other exhausting immune molecules (LAG-3, PD-1, CTLA4, CD244, and PD-1) exhibited significantly different expression profiles between normal brain tissues and GBM tissues according to the TCGA database, indicating their potential correlation with glioma progression." (PMID 33041828, 2020).
hepatocellular carcinoma (8 papers, 2018 to 2025). A malignant tumor that arises from hepatocytes. "Conversely, in human hepatocellular carcinoma (HCC), CD48‐overexpressing monocytes within the TME engage CD244+ NK cells, leading to transient activation followed by rapid exhaustion and cell death." (PMID 40959206, 2025).